GFAP (glial fibrillary acidic protein)
Diseases named in the same sentence as GFAP in open-access papers (continued):
Sharing a sentence is not in itself a finding about the gene and the disease.
meningoencephalitis (27 papers, 2013 to 2025). Inflammation of the meninges and brain, generally secondary to an infectious cause. "It showed a marked meningoencephalitis with astrocytic damage characterized by loss of GFAP and AQP4 within the lesions." (PMID 38310187, 2024). "A GFAP-related meningoencephalitis associated with lower limb radiculitis was finally retained, and the patient was treated with associated intravenous immunoglobulin (IVIg; 0.4 g/kg/day for 5 days)." (PMID 37540278, 2023). "In addition, ON may develop as part of anti-glial fibrillary acidic protein (GFAP) antibody-associated meningoencephalitis, and in association with anti-glycine receptor a1 subunit antibodies." (PMID 38867071, 2024). "GFAP-positive meningoencephalitis is currently presumed to be T-cell mediated, and the antibodies can be seen without association of distinct clinical-radiological features, but the presence of IgG GFAP-Ab provides a clue supporting immune-mediated disorder as a biomarker of the disease." (PMID 36726989, 2022). "A previously reported nivolumab-treated NSCLC patient with GFAP meningoencephalitis demonstrated limited response to high-dose corticosteroids and plasma exchange, ultimately requiring natalizumab rescue therapy." (PMID 40936919, 2025). "Meningoencephalitis and subcortical white matter lesions are the main manifestations of GFAP astrocytopathy, while seizures and cortical lesions are rare." (PMID 36688157, 2022). "The diagnosis was confirmed by the acute onset of meningoencephalitis and the detection of GFAP antibodies in the patient's CSF." (PMID 34160439, 2021). "We suggest that GFAP-IgG detection should be included in the comprehensive evaluation of patients with meningoencephalitis." (PMID 34160439, 2021). "Autoimmune glial fibrillary acidic protein (GFAP) astrocytopathy is a neurological disorder characterized by the presence of autoantibodies targeting GFAP, an intermediate filament protein expressed in astrocytes, leading to meningoencephalitis or meningoencephalomyelitis." (PMID 40502870, 2025). "Another Mayo Clinic study showed that among 10 patients with both bilateral optic disc edema and GFAP-Ab-positive meningoencephalitis, 100% (7/7) were GFAP-Ab positive in CSF, and 8 of 9 (89%) were positive in serum." (PMID 37101204, 2023). "For cases of acute encephalitis or meningoencephalitis type presenting with typical fever, headache, neck resistance, and impaired consciousness, we can accurately predict positive GFAP antibodies when combined with the characteristic symptoms of "tremor" and "bowel and Urinary dysfunction "." (PMID 37079256, 2023). "In CSF from patients with WNV meningoencephalitis, an increase of GFAP was noted; however, the detection of this protein in individuals presenting only WNV fever underlined that glial brain degradation could occur in the absence of severe clinical symptoms." (PMID 23874584, 2013). "Autoimmune glial fibrillary acidic protein (GFAP) astrocytopathy (GFAP-A) is a type of autoimmune corticosteroid-responsive meningoencephalitis that occurs with or without myelitis." (PMID 35447992, 2022).
Obesity (27 papers, 2016 to 2025). Accumulation of substantial excess body fat. "A recent study in older patients with T2DM and overweight or obesity explored longitudinal associations between cognition and plasma levels of Aß40, Aß42, total Tau, p-Tau181, glial fibrillary acidic protein (GFAP), and NfL." (PMID 40606939, 2025). "Glial fibrillary acidic protein (GFAP)/neurofilament light chain (NfL) may serve as monitoring tools for cognitive risk in T2D/obesity." (PMID 40842786, 2025). "Since obesity is associated with increased risk for several neurodegenerative disorders, we hypothesized that circulating NfL and GFAP levels could reflect neuronal damage in obese patients." (PMID 35551210, 2022). "Obesity due to deficient leptin receptor signaling in these ZDF rats was associated with significantly higher astrogliosis in the DVC but a marked reduction in density of GFAP-positive cells in the arcuate nucleus compared to wild-type control rats." (PMID 32152264, 2020). "The molecular weights of NfL (61.5 kDa35) and GFAP (50 kDa36) are similar to that of albumin (66.5 kDa), and thus, obesity could also lead to relatively higher loss of these proteins in urine, explaining the decreased circulating levels of NfL and GFAP in the obese." (PMID 35551210, 2022). "In contrast to our hypothesis plasma NfL and GFAP concentrations were lower in patients with obesity compared to lean subjects, but at six months after bariatric surgery with significant weight loss, NfL and GFAP levels were increased to the same level as in lean controls." (PMID 35551210, 2022). "For example, previous studies have demonstrated that HFD-consumption-induced obesity causes CNS inflammation, followed by astrogliosis and microgliosis in rodents, which can be recognized by elevations in their respective markers, including GFAP (an astrocytic marker) and Iba-1 (microglia marker)." (PMID 31963819, 2020). "In young adult female Wistar rats with diet-induced obesity, WS dry leaf powder reduced the expression of GFAP and IBA1 in the hippocampus along with other inflammatory markers." (PMID 39456417, 2024). "In animal models of obesity, gene and protein expression of the glial fibrillary acidic protein (GFAP), an astrocyte marker, are commonly higher in obese groups when compared to control animals." (PMID 36969815, 2023). "GFAP immunolabelling results are consistent with studies suggesting the activation of astrocytes in the cerebellum and hypothalamus during obesity." (PMID 36010611, 2022). "We observed increased GFAP immunoreactivity and altered astrocyte morphology in the brains of 1-month old mice prior to obesity in congenital knockout mouse models of BBS1, BBS2, BBS4, and BBS8." (PMID 31072410, 2019). "We observed increased GFAP and VIMENTIN immunoreactivity in multiple different congenital knockout mouse models of BBS prior to the development of obesity, suggesting that loss of BBSome function causes reactive astrocytes." (PMID 31072410, 2019). "In further support of this, the association between NfL (or GFAP) and eGFR was driven by the subjects with obesity, whereas no such correlation was found in the lean individuals." (PMID 35551210, 2022). "In conclusion, our data suggest that decreased circulating NfL and GFAP levels found in patients with obesity may be based on their enhanced glomerular filtration rate." (PMID 35551210, 2022). "We have addressed the possibility that blocking IL-6 trans-signaling in the brain could have an effect in the triple transgenic 3xTg-AD mouse model of AD and/or in obesity progression, by crossing 3xTg-AD mice with GFAP-sgp130Fc mice." (PMID 32630818, 2020). "According to previous studies, HFD intake and obesity induce glia activation and central neural inflammation, as demonstrated by an increase of the gliosis marker GFAP as well as pro-inflammatory mediators (NF-kB, IL-6 and IL-1β) and the infiltration of immune cells." (PMID 30134549, 2018).
Obesity (continued). "While studies of obesity identified astrocyte reactivity in multiple brain regions, including the PVN, our study appears to be the first to find an increase in GFAP, indicative of astrocyte reactivity, in the PVN of hypertensive rats." (PMID 39627570, 2025). "Significant increases in glial fibrillary acidic protein (GFAP) immunoreactive astrocytes were observed in the hippocampus and frontal and parietal cortices in rodent models of obesity." (PMID 31992978, 2019). "Researchers recommend investigating adipocytokines, neuroinflammation, and biomarkers such as GFAP and NfL in metabolism-related disorders like T2D and obesity to clarify their roles independent of amyloid and tau pathology." (PMID 40842786, 2025). "GFAP: Model 6 was again best fitting and showed faster average increases in those with Stage 3 kidney disease, higher average values in those with Stage 3 kidney disease, or higher APOE‐npscore and lower average values in men and people with obesity." (PMID 38970274, 2024). "Grade III GFAP expression was predominant in the control, T2DM and obesity groups." (PMID 37296126, 2023). "Chloe Stenkamp16 and his colleague reported that obesity and diabetes progressed in high-fat diet mice did not alter S100β, Sox10 and GFAP expression in myenteric of EGC." (PMID 30140011, 2018). "Obesity combined with Aβ infusion significantly increased IBA-1 immunoreactivity relative to vehicle-treated control mice (F = 2.96, p = 0.05) and increased GFAP immunoreactivity compared to all other groups (F = 5.13, p = 0.004)." (PMID 27578213, 2016). "In order to confirm the interplay among obesity, NLRP3 inflammasome activation and enteric gliosis, we performed a double‐staining immunofluorescence analysis to investigate ASC specks, reflecting an active status of the inflammasome, at level of mucosal and neuromuscular GFAP‐positive glial cells." (PMID 39287080, 2025). "To determine how obesity affects neuroinflammation in female mice, we examined the mRNA expression levels of proinflammatory cytokines (TNFα, IL1β, and IL6) and markers of microgliosis (Iba1) and astrogliosis (GFAP) in three distinct brain subregions (hypothalamus, hippocampus, and cerebral cortex)." (PMID 39230054, 2024). "In the HFD rats, we observed that astrocyte structural protein GFAP was increased and that there were morphologic changes in astrocytes in the ARCN, suggesting astrocytes may play an important role in the pathology of obesity." (PMID 31803004, 2019).
oligodendroglioma (27 papers, 2010 to 2025). A well-differentiated (WHO grade II), diffusely infiltrating neuroglial tumor, typically located in the cerebral hemispheres. "In oligodendrogliomas, in three out of five cases, the GFAP staining was mainly in the background reactive astrocytes." (PMID 35885538, 2022). "The reactive GFAP-expressing cells in oligodendroglioma are limited to the reactive astrocytes in the background and two forms of transitional neoplastic oligodendrocytes (gliofibrillary astrocytes and minigemistocytes)." (PMID 35885538, 2022). "Only one tumor, initially diagnosed as pediatric oligodendroglioma, showed strong GFAP immunoreactivity related to numerous entrapped reactive astroglial cells and dense network of their processes in the tumor background." (PMID 32650833, 2020). "Immunostaining was positive for glial fibrillary acidic protein (GFAP) and the mutated form of IDH1, and therefore excluded any diagnosis other than oligodendroglioma metastasis." (PMID 31248444, 2019). "Postoperative histopathological staining results included OLIGO-2(+) and GFAP(-), leading to a pathological diagnosis of oligodendroglioma of the ciliary body in the right eye (WHO grade II)." (PMID 20969790, 2010). "Interestingly, GFAP and S-100 expression was detected in oligodendroglioma ingredients of the tumor (D5, D7)." (PMID 25879429, 2015). "Furthermore, part of the tumor cells in oligodendrogliomas may show a gliofibrillary or minigemistocytic phenotype with strong staining for glial fibrillary acidic protein (GFAP) of the cytoplasm, or rarely even signet-ring cell morphology." (PMID 25943885, 2015). "To validate this result, we performed immunofluorescence staining on oligodendroglioma and anaplastic astrocytoma tissue to assess the expression of METTL8 and GFAP." (PMID 38824202, 2024). "In this case, the patient had received the clinical diagnosis of neurofibromatosis type I. Case #17 showed an oligodendroglioma-like morphology (see later), diffuse OLIG2 nuclear positivity, but only focal expression of GFAP." (PMID 37891325, 2023). "Per histopathological grade a significantly increased relative number of GFAP+CD16+ monocytes was found compared to healthy controls in diffuse astrocytoma (P < 0.005), oligodendroglioma (P < 0.001), GBM (P < 0.001) and brain metastasis (P < 0.001)." (PMID 33501422, 2021). "OLIGO-2 expression is relatively specific for oligodendrogliomas, and the combination of OLIGO-2 and GFAP expression provides further support for the diagnosis." (PMID 20969790, 2010). "In addition, some GFAP-negative samples in this experiment were oligodendroglioma (WHO II), and circ0004214 was also lowly expressed in these samples." (PMID 36831736, 2023). "SHG-139 intracranial xenografts expressed GFAP, but no overt oligodendroglioma was observed." (PMID 25879429, 2015). "Furthermore, immunopositivity of cytokeratins and absence of GFAP expression are useful markers for the distinction of a metastatic carcinoma located in the pineal region from a low grade oligodendroglioma." (PMID 20849631, 2010). "With findings of cells exhibiting oligodendroglioma-like appearance, strong OLIG2 and synaptophysin expression, and absence of widespread GFAP expression, the diagnosis was revised to DGONC." (PMID 40475045, 2025). "As our case demonstrated cells exhibiting oligodendroglioma-like appearance, strong OLIG2 and synaptophysin expression, and absence of widespread GFAP expression, the diagnosis of DGONC was assigned based on these morphological features." (PMID 40475045, 2025).
schwannoma (27 papers, 2008 to 2025). A benign, usually encapsulated slow growing tumor composed of Schwann cells. "It is widely acknowledged that peripheral nerves are more prone to diffuse GFAP expression than cranial nerve‐associated schwannomas." (PMID 39158355, 2024). "Some studies propose that the expression of keratin in schwannomas is attributed to cross‐reactivity with GFAP, as both keratin and GFAP are partially homologous proteins." (PMID 39158355, 2024). "GFAP antibodies facilitate the differential diagnosis of peripheral nervous sheet tumors such as Schwannomas and neurofibromas in fish." (PMID 37760333, 2023). "In hybrid perineurioma/schwannoma, Sox10 and GFAP expression was restricted to the part of the schwannoma, whereas the perineurioma regions expressed claudin-1 moderately to strongly and were negative for Sox10 and GFAP." (PMID 35622732, 2022). "Grossly, schwannomas are white, encapsulated, and well-circumscribed lesions that stain strongly positive for S100, GFAP, and CD57." (PMID 34931151, 2021). "After resection, the histopathological analysis showed a schwannoma with diffuse expression of S100 protein and GFAP." (PMID 34289875, 2021). "The S-100 protein and NSE stained positively in all Schwannomas; Vimentin presented negativity in 3 (21.4%) patients and positivity in 11 (78.6%) patients; GFAP presented negativity in 1 (33.3%) and positivity in 2 (66.6%) patients." (PMID 30710876, 2019). "GI-schwannomas are supposed to arise from the myenteric plexus of the GI wall because of their immunophenotypic similarities; both schwannomas and myenteric plexus cells express S-100 protein and GFAP." (PMID 30045739, 2018). "At pathology, 97.9, 13.7, and 5.3% of schwannomas stained positive for S100, vimentin, and GFAP, respectively." (PMID 29970075, 2018). "Immunohistochemical analysis can easily separate schwannomas from perineuriomas, since the former are positive for S-100 protein and glial fibrillary acidic protein and the latter are positive for EMA." (PMID 21437510, 2011). "The cells also expressed S-100 protein and glial fibrillary acidic protein, confirming the diagnosis of a cellular schwannoma." (PMID 18518995, 2008). "This was a cellular schwannoma, which showed, in addition to the expression of S-100 protein and GFAP, strong and diffuse expression of cytokeratins." (PMID 18518995, 2008). "Early observations of schwannomas suggest that GFAP positivity may be more prevalent in peripheral spinal, retroperitoneal, and mediastinal schwannomas." (PMID 39158355, 2024). "Schwannomas may also express glial fibrillary acidic protein (GFAP) and newer markers such as podoplanin, calretinin, and SOX10." (PMID 39677119, 2024). "Schwannomas also stain positively for Leu-7antigen, GFAP, and vimentin." (PMID 34175679, 2021). "Finally, the negativity for GFAP and calretinin in the investigated cases was also consistent with the diagnosis of neurofibroma, despite not being specifically suggestive of this diagnosis since a variable degree of GFAP positivity has been reported among mammal and fish schwannomas." (PMID 34573587, 2021). "Immunohistochemical staining results of other benign schwannomas showed positivity for S‐100,26, 29, 30 SOX10, Vimentin, and GFAP, and negativity for SMA, EMA, CD34, and CD117." (PMID 36440500, 2023). "The immunohistochemistry panel confirmed the diagnosis of neurilemmoma: PS100(+), collagen IV(+), and vimentin(+), but also unveiled a diffuse labelling for glial fibrillary acidic protein (GFAP) in both Antony patterns." (PMID 27446622, 2016). "The pathological diagnosis was Schwannoma and immunohistochemical testing showed Vimentin (+), S-100 (+), MBP (+), CD56 (+), GFAP (+), Ki-67 (+), Desmin (−), SMA (−), EMA (−), CD34 (positive in tumor vessels)." (PMID 23432938, 2013). "The classic schwannoma was the only one that was completely negative for claudin-1 and showed strong reactivity for Sox10 and moderate reactivity for GFAP." (PMID 35622732, 2022).
schwannoma (continued). "Schwannoma tumorlets in the DRGs of mGFAP-Cre;Smarcb1flox/flox;Nf2flox/flox mice were negative for SMARCB1 and merlin staining, about 60% were positive for S100 protein staining, and all were positive for GFAP and FABP7." (PMID 28824165, 2017). "In immunostaining studies schwannomas are always positive for proteins S100, positive for glial fibrillary acidic protein and CD57 marker but less constant and always negative for muscle markers." (PMID 25159340, 2014). "Unlike classical schwannomas, retroperitoneal cellular schwannomas commonly express GFAP and CK, suggesting that they may originate from unmyelinated Schwann cells, unlike classical schwannoma, which may originate from myelinated Schwann cells." (PMID 39757665, 2025). "However, the schwannoma diagnosis was supported by light microscopy and corroborated by S100 protein and GFAP expression and CD34 negative." (PMID 34289875, 2021). "This helps to differentiate it from schwannoma, which is S-100 positive and GFAP negative." (PMID 23476839, 2013). "Based on our results, we consider Sox10, claudin-1, GFAP, and Ki-67 useful in the diagnosis of NST, whereas CNPase was negative in almost all cases, except for classical schwannoma, which was only mildly positive." (PMID 35622732, 2022).